CD4 (CD4 molecule)
Diseases named in the same sentence as CD4 in open-access papers (continued):
Sharing a sentence is not in itself a finding about the gene and the disease.
adult T-cell leukemia/lymphoma (continued). "Human T-cell leukemia virus type 1 (HTLV-1) is a retrovirus that causes adult T-cell leukemia/lymphoma (ATL), a cancer of infected CD4+ T-cells." (PMID 35504920, 2022). "Adult T cell leukemia/ lymphoma (ATLL) is infected clonal T-cell (CD4+, CD25+) progression, proliferation, and malignant transformation with a very poor prognosis." (PMID 35911645, 2022). "HTLV-1 is a highly oncogenic yet neglected retrovirus, which primarily infects CD4+ T-cells in vivo and causes incurable diseases like HTLV-1-associated inflammatory conditions or Adult T-cell leukemia/lymphoma (ATLL) after lifelong viral persistence." (PMID 35360738, 2022). "Human T-cell leukemia virus type 1 (HTLV-1), the cause of adult T-cell leukemia/lymphoma (ATLL), is a retrovirus, which integrates into the host genome and persistently infects CD4+ T-cells." (PMID 34073995, 2021). "HTLV-1 is the cause of adult T-cell leukemia/lymphoma (ATLL), a CD4 + CD25 + CD62L + FoxP3 + CCR4 + CADM1 + effector memory T-cell lymphoproliferative disorder that accounts for 5% of T-cell lymphomas and leukemias." (PMID 35056532, 2021). "HTLV-1 predominantly infects CD4+ T cells and infection is associated with the development of a CD4+CD25+ malignancy, adult T-cell leukemia/lymphoma (ATLL), in ~5% of infected individuals after a long latent period (about 60 years)." (PMID 33362245, 2020). "We documented a case of adult T-cell leukemia/lymphoma (chronic type), which had a phenotype of CD4+CD25+CD69+CD103+ TRM cells, indicating the TRM property of this case and the presence of TRM malignancy in cutaneous lymphomas other than MF." (PMID 33633737, 2020). "Adult T-cell leukemia (ATL) is a highly aggressive CD4+ T-cell leukemia characterized by clonal integration of the human T-cell leukemia virus type I (HTLV-I) in tumor cells." (PMID 33167425, 2020). "Adult T-cell leukemia/lymphoma (ATL) is an aggressive and incurable malignancy of mature CD3+, CD4+, CD25+, CD7– T cells caused by human T-cell lymphotropic virus type-1 (HTLV-1), which was initially described in 1977 by Takatsuki (2005)." (PMID 32793179, 2020). "Adult T-cell Leukemia (ATL) is a lymphoproliferative disease of CD4+ T-cells infected with Human T-cell Leukemia Virus type I (HTLV-1)." (PMID 31251786, 2019). "Few years earlier, Adult T-cell Leukemia/Lymphoma or ATLL (i.e. an aggressive malignancy of CD4+ T-cells) had been described in Japan." (PMID 31843020, 2019). "Human T-cell lymphotropic virus type 1 (HTLV-1) is the causative agent of adult T-cell leukemia (ATL), an aggressive CD4+/CD25+ T-cell malignancy and of a severe neurodegenerative disease, HTLV-1 associated myelopathy/tropical spastic paraparesis (HAM/TSP)." (PMID 29515558, 2018). "About 5% of infected individuals develop an aggressive malignancy of mature CD4+ T-cells termed adult T-cell leukemia/lymphoma (ATLL) or a progressive demyelinating neurological disease termed tropical spastic paraparesis/HTLV-associated myelopathy (TSP/HAM)." (PMID 29780367, 2018). "Although most HTLV-1 infected individuals remain asymptomatic carriers (AC) lifelong, about 3–5% of them develop, after many years of clinical latency, a severe malignancy of CD4+ T cells, known as Adult T-cell Leukemia (ATL)." (PMID 29312275, 2017). "Human T-cell leukemia virus type 1 (HTLV-1) is etiologically associated with adult T-cell leukemia (ATL), an aggressive and lethal malignancy of CD4+ T cells, and with HTLV-1-associated myelopathy/tropical spastic paraparesis (HAM/TSP)." (PMID 28103322, 2017). "Human T-cell leukemia virus type 1 (HTLV-1) infects CD4+ T cells and induces proliferation of infected cells in vivo, which leads to the onset of adult T-cell leukemia (ATL) in some infected individuals." (PMID 26735971, 2016). "Adult T-cell leukemia (ATL) is caused by the Human T-cell leukemia virus type 1 (HTLV-1) and is a highly aggressive CD4+ T-cell leukemia characterized by clonal integration of HTLV-1 in leukemic cells." (PMID 26597716, 2015).
adult T-cell leukemia/lymphoma (continued). "The majority of the HTLV-1 proviral load is found in CD4+ T cells, and the phenotype of adult T cell leukemia (ATL) is typically CD4+." (PMID 26552867, 2015). "Human T-cell leukemia virus type 1 (HTLV-I) is a human retrovirus associated with adult T-cell leukemia (ATL), an aggressive CD4 T-cell proliferative disease with dismal prognosis." (PMID 25185513, 2014). "BLV and HTLV-1 are related deltaretroviruses, and higher percentages of PD-1 expression were observed in CD4+ T cells from blood of HTLV-1-infected patients with adult T-cell leukemia." (PMID 23876077, 2013). "Adult T-cell leukemia/lymphoma (ATLL) is an aggressive malignant disease of mature CD4+ regulatory T lymphocytes." (PMID 23383087, 2013). "HTLV-1 is the causative agent of adult T-cell leukemia/lymphoma (ATLL), an aggressive malignancy of mature CD4+ T-cells, and of tropical spastic paraparesis/HTLV-1-associated myelopathy (TSP/HAM), a demyelinating neurodegenerative disease." (PMID 21994786, 2011). "Human T-cell leukemia virus type 1 (HTLV-1) is the etiologic agent of adult T-cell leukemia, a malignancy characterized by uncontrolled proliferation of virally-infected CD4+ T-cells." (PMID 20653953, 2010). "Human T-cell leukemia/lymphoma virus type-1 (HTLV-1) is the causative agent of Adult T-cell Leukemia/Lymphoma (ATLL), an aggressive CD4+ leukemia/lymphoma." (PMID 20132553, 2010). "Adult T cell leukemia results from the malignant transformation of a CD4+ lymphoid clone carrying an integrated HTLV-1 provirus that has undergone several oncogenic events over a 30-60 year period of persistent clonal expansion." (PMID 20222966, 2010). "Human T-lymphotropic virus type 1 (HTLV-1) is the etiologic agent of a severe and fatal lymphoproliferative disease of mainly CD4+ T cell origin, adult T cell leukemia, which develops after prolonged viral persistence." (PMID 19014482, 2008). "In contrast to HIV-1, which is responsible for the depletion of the CD4+ cell population, HTLV-1, the etiological agent of Adult T cell leukemia/lymphoma (ATLL), causes lymphocyte transformation." (PMID 17433108, 2007). "HTLV-1 is the causative agent of two main diseases: adult T-cell leukemia/lymphoma (ATLL), a chemotherapy-resistant non-Hodgkin’s malignancy of CD4+ T cells, and HTLV-1-associated myelopathy/tropical spastic paraparesis (HAM/TSP), a chronic, progressive neurogenerative disease." (PMID 39902961, 2025). "Human T-cell leukemia virus type 1 (HTLV-1), the first oncogenic human retrovirus, causes adult T-cell leukemia/lymphoma (ATLL), an aggressive neoplasm of mature CD4+ T-cells that is incurable in most patients and is associated with a median survival of less than 1 year." (PMID 41157604, 2025). "HTLV-1 is the causative infectious agent of adult T-cell leukemia/lymphoma (ATL), an aggressive and fatal CD4+ T-cell malignancy that develops in approximately 5–10% of infected individuals after a long clinical latency period that spans upwards of five decades." (PMID 35062342, 2022). "HTLV-1 can induce excessive clonal proliferation of CD4+ T cells and may result in cancer called Adult T Cell Leukemia-Lymphoma (ATLL) that has four clinical subtypes: smoldering, chronic, acute, and lymphoma." (PMID 33451365, 2021). "However, after a long latency period, approximately 5% of HTLV-1 carriers develop adult T-cell leukemia/lymphoma (ATLL), a CD4+ T-cell malignancy, and 1–4% develop HTLV-1 associated myelopathy/tropical spastic paraparesis (HAM/TSP), a chronic inflammatory disease." (PMID 34314415, 2021). "The relationship of the polymorphism with the T CD4+ lymphocytes and IL-8 is indicative of the constitution of an atypical pro-inflammatory immune network, however, already observed in HTLV-1 infection, mainly in patients with Adult T-cell leukemia (ATL)." (PMID 33213373, 2020).
adult T-cell leukemia/lymphoma (continued). "After a long latency, 3–5% of infected individuals will develop either a severe malignancy of CD4+ T cells, known as Adult T-cell Leukemia (ATL) or a chronic and progressive inflammatory disease of the nervous system designated Tropical Spastic Paraparesis/HTLV-1-Associated Myelopathy (HAM/TSP)." (PMID 29312275, 2017). "Adult T-cell leukemia (ATL) is a CD4+ T-cell neoplasm with a poor prognosis." (PMID 26597716, 2015). "Large scale sequencing of small RNA libraries was used to identify small non-coding RNAs expressed in normal CD4+ T cells compared to cells transformed with human T-cell leukemia virus type 1 (HTLV-1), the causative agent of adult T-cell leukemia/lymphoma (ATLL)." (PMID 24966867, 2014). "Human T-cell leukemia virus type 1 (HTLV-1) is the first retrovirus that is associated with human diseases including an aggressive leukemia derived from CD4+ T cells, adult T-cell leukemia (ATL), and chronic inflammatory diseases of the central nervous system, lung, or skin." (PMID 21347344, 2011). "However, HTLV-1 is the etiological agent of a malignant CD4 lymphoproliferation (adult T-cell leukemia [ATL]) and a chronic progressive neuromyelopathy (tropical spastic paraparesis/HTLV-1-associated myelopathy [TSP/HAM])." (PMID 16725042, 2006). "Human T-cell leukemia virus type I (HTLV-I) is an oncogenic virus whose infection can cause diverse diseases, most notably adult T-cell leukemia/lymphoma (ATL or ATLL), an aggressive and fatal malignancy of CD4 T cells." (PMID 38722890, 2024). "The WHO-HAEM5 and the International Consensus Classification (ICC) both characterize adult T-cell leukemia/lymphoma (ATLL) as a type of peripheral T-cell cancer originating from CD4-positive T-cells infected with human T-cell leukemia virus (HTLV) type 1." (PMID 38535155, 2024). "The first is adult T-cell leukemia/lymphoma (ATLL) associated with HTLV, a malignant proliferation of CD4+ T lymphocytes." (PMID 39041060, 2024). "Adult T-cell leukemia/lymphoma (ATLL) is associated with human T-cell lymphotropic virus type 1 (HTLV-1) infection and is characterized by neoplastic proliferation of CD4-positive T-cells." (PMID 35386167, 2022). "Adult T-cell leukemia/lymphoma (ATLL) cells showed typical irregular nuclear contours and were characterized by moderate CD2, CD4, and CD5, loss of surface CD3, CD7, and CD26, and dim-to-negative CD279." (PMID 35299754, 2022). "Adult T-cell leukemia/lymphoma (ATLL) is a malignancy of mature T cells caused by human T-cell leukemia virus type I. Approximately 50% of ATLL patients exhibit skin lesions where malignant CD4+CD25+ T cells histologically show epidermotropism." (PMID 33633737, 2020). "Adult T-cell leukemia/lymphoma (ATLL) consists of CD4+ T-cell neoplasm and frequently presents leukemic changes and tumor cell invasion in various organs, including the GI tract." (PMID 33087157, 2020). "Once acquired, HTLV-1 infections persist life-long, most patients remaining asymptomatic viral reservoirs ensuring the transmission chain, but about 4% develop adult T-cell leukemia/lymphoma (ATLL), a highly aggressive CD4+ T-cell malignancy." (PMID 29940042, 2018). "Human T-cell leukemia virus type 1 (HTLV-1) is the etiological agent of adult T-cell leukemia/lymphoma (ATLL), an aggressive malignant proliferation of activated CD4+ T lymphocytes." (PMID 29566098, 2018). "HTLV-1 (Human T-cell leukemia virus, type 1) is the etiological agent of adult T-cell leukemia/lymphoma (ATLL), an aggressive and fatal form of leukemia characterized by the malignant expansion of activated CD4+ T-cells." (PMID 29566098, 2018). "HTLV-1 is indeed the etiologic agent of adult T-cell leukemia/lymphoma (ATLL), a very aggressive malignant proliferation of CD4+ T lymphocytes, which appears in 2–5% of infected individuals." (PMID 28742148, 2017).
adult T-cell leukemia/lymphoma (continued). "Adult T-cell leukemia/lymphoma (ATLL) is an aggressive and fatal malignancy of CD4+ T-lymphocytes infected by the Human T-Cell Virus Type 1 (HTLV-1)." (PMID 26265053, 2015). "This blood-borne pathogen is the causative infectious agent of adult T-cell leukemia/lymphoma (ATLL), a disease of CD4+ T-cells." (PMID 26729154, 2015). "Reprogramming of gene transcription sustains HTLV-1 viral persistence and ultimately leads to the development of adult T-cell leukemia/lymphoma (ATLL) from a CD4+-infected clone in a minority of carriers after a prolonged latency." (PMID 25519886, 2014). "Adult T-cell leukemia/lymphoma (ATLL), a severe mature T-cell tumor, has been observed to involve the mitral valve, showing CD4+ T-cell infiltration in chronic cases." (PMID 39421157, 2024). "In contrast, in adult T-cell leukemia/lymphoma (ATLL), CAFs promote CD4+ T cell proliferation via FGF7-FGF1 and PDGFA-PDGFRA/B signaling." (PMID 39555055, 2024). "About 3–5% of infected patients develop an aggressive neoplasm of mature CD4+ T-cells named adult T-cell leukemia/lymphoma (ATLL) or a neurological disease named tropical spastic paraparesis/HTLV-associated myelopathy (TSP/HAM) after a latency period of decades (ATLL) or years (TSP/HAM)." (PMID 29467726, 2018). "The Tax protein of human T-cell leukemia virus type 1 (HTLV-1) is crucial for the development of adult T-cell leukemia (ATL), a highly malignant CD4+ T cell neoplasm." (PMID 28103322, 2017). "Human T-cell leukemia virus (HTLV)-1 is a human retrovirus and the etiological agent of adult T-cell leukemia/lymphoma (ATLL), a fatal malignancy of CD4/CD25+ T lymphocytes." (PMID 26205403, 2015). "HTLV-1 infection is etiologically linked to the development of the neuroinflammatory disorder HTLV-1 associated myelopathy/tropical spastic paraparesis (HAM/TSP) and adult T-cell leukemia (ATL), an aggressive CD4+CD25+ malignancy." (PMID 25340740, 2014). "Human T lymphotrophic virus type 1 (HTLV-1) is the etiological agent of adult T cell leukemia/lymphoma (ATL), which in its acute form is a highly aggressive CD4+ T-cell cancer that is refractory to standard therapies." (PMID 17634129, 2007). "Adult T-cell leukemia (ATL) is an extremely aggressive T-cell leukemia, and it is characterized by malignant expansion of CD4 positive T-cells infected with human T-cell leukemia virus type 1 (HTLV-1)." (PMID 16042787, 2005). "HTLV-1 is the etiologic infectious agent of both adult T-cell leukemia/lymphoma (ATL), an aggressive and fatal disease of CD4+ T cells, and HTLV-1-associated myelopathy/tropical spastic paraparesis (HAM/TSP), a chronic inflammatory disease of the central nervous system (CNS)." (PMID 33425776, 2020). "Human T-cell lymphotropic/leukemia virus type 1 (HTLV-1) is the etiological agent of adult T-cell leukemia (ATL), a malignancy of CD4+/CD25+ T cells and of a chronic inflammatory disease called HTLV-1 associated myelopathy/tropical spastic paraparesis (HAM/TSP)." (PMID 29515558, 2018). "On the contrary, ZEB1 is a candidate tumor suppressor gene in adult T-cell leukemia/lymphoma (ATLL), where it contributes to TGF-β1-mediated growth suppression resistance of malignant CD4+ T cells and ZEB1 mutant mice frequently undergo spontaneous CD4+ T-cell lymphomas." (PMID 30518749, 2018). "Human T-cell leukemia virus 1 (HTLV-1) infects approximately 20 million people worldwide and is the etiological agent of adult T-cell leukemia (ATL), an aggressive CD4+CD25+ malignancy that occurs in a small percentage of infected individuals after a long latent period." (PMID 25340740, 2014). "Finally, HTLV-1–associated adult T-cell leukemia/lymphoma (ATLL) and some types of peripheral T-cell lymphoma–not otherwise specified (PTCL-NOS) may also involve HE with circulating CD3− CD4+ T cells, and as such also constitute potential differential diagnoses." (PMID 37122022, 2023).
Crohn disease (123 papers, 2006 to 2026). A gastrointestinal disorder characterized by chronic inflammation involving all layers of the intestinal wall, noncaseating granulomas affecting the intestinal wall and regional lymph nodes, and transmural fibrosis. "We found that CD28 expression on CD39+ secreting CD4 Treg cells in the peripheral blood was negatively associated with the risk of Crohn disease." (PMID 39058862, 2024). "TNF-α is also released and has been associated with an elevation in CD4+ and FoxP3+ regulatory T cells in the mucosa of Crohn’s disease patients." (PMID 37740772, 2024). "The immune-pathology in Crohn’s disease is linked to dysregulated CD4+ T cell responses biased towards pathogenic TH17 cells." (PMID 35760777, 2022). "Intestinal macrophages in patients with Crohn’s disease induce the Th1 and Th17 polarization of naïve CD4+ T cells, which seems to be caused by the accumulation of immature macrophages in the total macrophage population of patients with Crohn’s disease." (PMID 33738283, 2021). "We were able to show that CD69+CD103+ cells with a TRM phenotype are increased in the lamina propria of patients with ulcerative colitis (UC) and Crohn’s disease (CD) and that high levels of CD4+ TRM cells in IBD patients are associated with early relapse." (PMID 33542725, 2020). "For T cells, we evaluated IFN-γ and IL-17A production in CD4+ T cells, as both have been implicated in Crohn's disease pathology." (PMID 28892060, 2017). "Thus, the high proportion of naïve CD4+ T cells was associated with reduced risk of Crohn disease, which is in accordance with our findings." (PMID 39058862, 2024). "Moreover, CD27 and CD28 downregulation on CD4+ T cells has been previously associated with other intestinal inflammatory diseases such as Crohn’s Disease." (PMID 38239362, 2023). "Moreover, a recent single-cell RNAseq study integrating cell-specific-eQTL to RNASET2 disease risk variants provides strong evidence that multiple immune cell subsets including CD4+ T cells contribute to Crohn’s disease causation." (PMID 36466822, 2022). "Healthy-derived ASCs were unable to activate CD4+ T-lymphocytes, whereas Crohn’s disease-derived ASCs increased CD4+ T-cells proliferation by approximately 3%, which was associated with an increase in IL-2 (3.325 pg/mL vs. 9.615 pg/mL, respectively), a cytokine released by activated CD4+ T-cells." (PMID 33924264, 2021). "Higher GSDMA expression in naïve/central‐memory CD4+ T cells was protective in UC and Crohn disease, whereas up‐regulation in cytotoxic CD8+/natural‐killer cells increased the risk for hidradenitis suppurativa and ankylosing spondylitis." (PMID 41442179, 2026). "We previously reported that a subset of CD4+ TRM appears in the affected lesion of Crohn’s disease (CD) patients." (PMID 40906156, 2025). "Here, we employed multilayered single-cell analytic approaches including chromatin, gene, and protein profiling to characterize a unique CD4+ TRM subset present in the inflamed gut mucosa of Crohn’s disease patients." (PMID 40906156, 2025). "ATG7 level was markedly elevated in inflamed mucosa tissues and peripheral blood CD4+ T cells of patients with active Crohn's disease compared to healthy individuals." (PMID 40887825, 2025). "Both TNFhi CD4+ TRM cells and IL17Ahi CD4+ TRM cells from patients with Crohn’s disease exhibited downregulation of the cellular response to stress pathway and lower ISR scores compared to healthy controls." (PMID 40050432, 2025). "In particular, CD4+ tissue-resident memory T (T_RM) cells have been found to be expanded in Crohn’s disease and are the major source of mucosal tumor necrosis factor α (TNFα), a principal mediator of intestinal injury." (PMID 38420127, 2024). "In previous studies, CD4 T cells were found to play a key role in the pathogenesis of Crohn’s disease." (PMID 38420127, 2024).